ID1 (inhibitor of DNA binding 1)
Diseases named in the same sentence as ID1 in open-access papers (continued):
Sharing a sentence is not in itself a finding about the gene and the disease.
infection (20 papers, 2006 to 2025). The state of being infected such as from the introduction of a foreign agent such as serum, vaccine, antigenic substance or organism. "The observations indicate that the high mink incubation rate raises Iu1+Id1 and that, as a result of virus mutation in minks, the number of human infections in the mutant strain increases dramatically." (PMID 37624336, 2023). "Id1 levels were also significantly up-regulated by infection with ACVR1 mutations relative to ACVR1 WT with ACVR1 G328V increasing Id1 protein levels the most." (PMID 30833574, 2019). "qRT-PCR analysis also showed that the angiogenesis-related genes, Angpt1, Id1, and Lyve1, were significantly upregulated at 10 weeks post-infection, and Pecam1 was significantly upregulated at 10–12 weeks post-infection." (PMID 41334166, 2025). "Intriguingly, Id1 protein declined in a dose-dependent manner according to the infection load of the HBV particles in HepG2-NTCP cells and decreased over time, even though HBV replication declined." (PMID 34975318, 2022). "As a result, LV-ID1 infection significantly increased both mRNA and protein expression levels of ID1." (PMID 33390793, 2021). "The IPA network analysis revealed that infection induced aged GF(P22)-specific DEGs were connected to each other and the upregulated genes (Id1, KLF10, GADD45b, and CSRNP1) were all mainly localized in the nucleus." (PMID 29190775, 2017). "In contrast, infection with the GDF5L373R virus resulted a reduction of inhibitor of differentiation 1 (ID1), which negatively regulates the expression of COL2A1 and SOX9." (PMID 29371961, 2017). "After 48 h of infection, Id1 knockdown induced a striking reversion to an epithelial-like phenotype in MDCK-EGFP-E47-shId1 cells compared to non-infected and control infected cells that remain fully mesenchymal." (PMID 23555842, 2013). "Knockdown of Id1 for longer time periods induced a massive cell death; indeed, repeated attempts to obtain stable infections with shId1 lentivirus were unsuccessful." (PMID 23555842, 2013). "The results demonstrated that the expression of ID1 was upregulated upon infection with AdBMP9." (PMID 37283947, 2023). "Results revealed that, during the first 3 h of infection, at least 96 transcripts associated with immune responses (e.g. ISGs, MX1, RSAD2, A3C, ID1, CRIP1, TRIM25 and MDA5), apoptosis (ID1, ATF3, TNFα, and RNF7), and pro-inflammatory responses (e.g. PD-L1, CCL8, CXCL10 and CCL17) were downregulated." (PMID 28388950, 2017). "The results indicate that there were only two scenarios in which the mutant strain could invade the original strain (i.e., Iu2+Id2>Iu1+Id1): when the transmission rate was high and the infection period was long, or when the transmission rate and the virus mutation rate were high." (PMID 37624336, 2023). "Moreover, the absence of the IFNγR rescued infection-driven BMP alterations: we found no loss of Bmp2 or Id1 expression, but reduced Grem2 expression in infected IFNγR KO mice compared to WT littermates." (PMID 35332152, 2022). "Our data indicate that acquisition of Ab to the ID1-ID2a protein after natural infection is not parity-dependent, but rather a “high” background level of cross-reactive Ab exists in the general population." (PMID 24505415, 2014).
adenocarcinoma (9 papers, 2010 to 2020). A common cancer characterized by the presence of malignant glandular cells. "Another study of high quality including 457 NSCLC patients also showed the independent prognostic value of Id1 levels for both stage I to stage IV patients that higher Id1 levels were associated with a shorter disease-free survival and overall survival in adenocarcinoma patients." (PMID 32410828, 2020). "Thus, in radically treated stages I to III patients and stage IV patients treated with chemotherapy, higher Id1 levels were associated with a shorter disease-free survival and overall survival in adenocarcinoma patients." (PMID 23311395, 2013). "In NSCLC, silencing of ID1 in radio/chemotherapy-resistant adenocarcinoma cells sensitized adenocarcinoma cells to radiotherapy and chemotherapy." (PMID 29169374, 2017). "Of note, H23 adenocarcinoma cells were shown to express low levels of Id1 even when grown in media containing increased levels of serum." (PMID 20414347, 2010). "We also noted overall significantly lower Id1 expression as compared to matched normal tissue (P = .02) in adenocarcinomas." (PMID 20414347, 2010). "More interestingly, we showed that Id1 downregulation in primary treatment-resistant adenocarcinoma cell lines sensitizes those cells to radiotherapy and chemotherapy treatment in vitro, although no mechanistic experiments where performed to explain that observation." (PMID 23311395, 2013). "Also, we observed that Id1 silencing may sensitize adenocarcinoma cells to radiotherapy and chemotherapy." (PMID 23311395, 2013). "Several of the identified mGISTIC regions harbored known or putative adenocarcinoma driver candidates, such as EGFR, MDM2, KRAS, MYC, TERT, MET, CCND1, NKX2-1/TITF1, CDK4, ERBB2, ID1, RB1, CDKN2A and PTEN." (PMID 24205279, 2013). "Id1 is frequently over-expressed in NSCLC, occurring in 70% of squamous and 50% of adenocarcinomas." (PMID 23593444, 2013). "No statistically significant mean Id1 expression differences were observed for each comparison, although increased Id1 expression in adenocarcinoma patients who reported smoking was nearly significant (P = .06) as compared to reported nonsmoker adenocarcinoma patients." (PMID 20414347, 2010).
liver (3 papers, 2018 to 2025). "Moreover, analysis of the Cancer Genome Atlas (TCGA) RNA-seq dataset further confirmed the decreased expression of ID1 in 372 liver HCC samples, compared to adjacent normal samples." (PMID 30154433, 2018).
cardiovascular disease (2 papers, 2021 to 2022). "No previous population studies reported an association of ID1 gene polymorphism with cardiovascular disease." (PMID 34440357, 2021).
colon (2 papers, 2018 to 2021). "Aberrantly high expression of inhibitor of differentiation 1 (ID1) contributes to the growth, self-renewal, and metastasis of a variety of tumors including colon cancer." (PMID 33990575, 2021).
hematologic disorder (1 paper, 2025). A disease involving the hematopoietic system. "Moreover, ID1 overexpression is a causal factor in hematologic malignancies." (PMID 41146039, 2025). "Given these multi-roles, ID1 emerges as a promising therapeutic target for differentiation therapy in hematologic disorders." (PMID 41146039, 2025). "Herein, we review the ID1 expression profile in the BM hematopoietic system, focusing on its dynamic changes and regulatory roles in lineage commitment and development, and further highlight its crucial roles and therapeutic implications in hematological disorders." (PMID 41146039, 2025).
metabolic disorders (1 paper, 2022). "In particular, overexpression of SERPINE1 and downregulation of ID1 genes, known to be associated with metabolic disorders, could represent other intracellular downstream mediators of GDF11 effects." (PMID 35920128, 2022).
ID1 also shares sentences with these, for which no sentence is quoted: pancreatic ductal adenocarcinoma (4 papers); Hepatitis (3); B-cell acute lymphoblastic leukemia (2); Burkitt lymphoma (2); embryonal carcinoma (2); gallbladder cancer (2); head and neck squamous cell carcinoma (2); liver disease (2); myelodysplastic syndrome (2); neurodegenerative disease (2); Stroke (2); type 2 diabetes (2); acute kidney injury (1); adenosquamous cell carcinoma (1); angina (1); atopic dermatitis (1); B-cell acute lymphoblastic leukaemia (1); benign prostatic hyperplasia (1); bone metastasis (1); cardiac disease (1); cavernomas (1); chronic hepatitis C (1); chronic myelomonocytic leukemia (1); colon adenocarcinoma (1); colon adenoma (1); coronary heart disease (1); cyst (1); diffuse intrinsic pontine glioma (1); diffuse large B-cell lymphoma (1); endothelial dysfunction (1).
A further 41 diseases each share a sentence with ID1 in 1 paper.